CTSA (cathepsin A)
Description:
Protective protein appears to be essential for both the activity of beta-galactosidase and neuraminidase, it associates with these enzymes and exerts a protective function necessary for their stability and activity. Also functions as an activator of the sialidase NEU1. This protein is also a carboxypeptidase and can deamidate tachykinins.
Synonyms: PPCA; PPGB; BSVD6; GLB2; GSL; NGBE
Tractability: Small molecule: a structure with a bound ligand is known; a high-quality ligand is known; it has a high-quality binding pocket; it belongs to a druggable protein family. Antibody: its Gene Ontology location is reachable by antibodies, with high confidence; UniProt predicts a signal peptide or a membrane-spanning region. PROTAC: ubiquitination databases record sites on it; its protein half-life has been measured; a small molecule that binds it is known.
Target class: Enzyme; Serine protease; Serine protease SC clan; Protease; Serine protease S10 family
Gene: Protein-coding gene on chromosome 20 (45,890,144 to 45,898,949, forward strand). Ensembl gene ENSG00000064601.
Subcellular location: Lysosome
Subcellular location (Human Protein Atlas): Vesicles
Pathways (Reactome):
Immune System: MHC class II antigen presentation; Neutrophil degranulation
Disease: Defective NEU1 causes sialidosis
Metabolism: Glycosphingolipid catabolism
Metabolism of proteins: Sialic acid metabolism
Gene Ontology:
Molecular function: carboxypeptidase activity; enzyme activator activity; serine-type carboxypeptidase activity
Biological process: negative regulation of chaperone-mediated autophagy; proteolysis; regulation of protein stability; intracellular protein transport; regulation of chaperone-mediated autophagy
Cellular component: extracellular exosome; lysosome; membrane; azurophil granule lumen; endoplasmic reticulum; extracellular region; lumenal side of lysosomal membrane; lysosomal lumen
Genetic constraint (gnomAD): Loss-of-function variants: 42 observed, 63.82 expected, observed/expected ratio (o/e) 0.66, 90% interval 0.51 to 0.85. The upper end of that interval is the gene's LOEUF score, 0.85, which puts it in group 3 of 6, group 1 being the genes least tolerant of losing a copy. Missense variants: 496 observed, 607.29 expected, observed/expected ratio (o/e) 0.82, 90% interval 0.76 to 0.88. Synonymous variants: 215 observed, 246.51 expected, observed/expected ratio (o/e) 0.87, 90% interval 0.78 to 0.98.
Gene-disease validity (ClinGen):
ClinGen rates the evidence that CTSA causes each of these diseases.
galactosialidosis (autosomal recessive): Definitive. A lysosomal storage disease characterized by coarse facial features, macular ''cherry red spot'', and dysostosis multiplex.
Homologues: Orthologues: chimpanzee CTSA (99% identical), macaque CTSA (98% identical), dog CTSA (90% identical), pig CTSA (89% identical), guinea pig CTSA (87% identical), mouse Ctsa (87% identical), rat Ctsa (87% identical), rabbit CTSA (80% identical), zebrafish ctsa (62% identical), tropical clawed frog ctsa (60% identical). Paralogues in human: CPVL (26% identical), SCPEP1 (22% identical).
Diseases named in the same sentence as CTSA in open-access papers:
CTSA is named in the same sentence as 81 diseases in open-access papers, as found by Europe PMC text mining. Sharing a sentence is not in itself a finding about the gene and the disease. The quoted sentences say what the papers report.
galactosialidosis (31 papers, 2007 to 2025). "Cathepsin A‐related arteriopathy with strokes and leukoencephalopathy (CARASAL) is a cerebral small vessel disease associated with a recessive mutation in the gene encoding cathepsin A that causes galactosialidosis, a lysosomal storage disorder." (PMID 39253904, 2025). "Here we report a Japanese patient with juvenile/adult-type galactosialidosis carrying a homozygous c.692+3A>G CTSA variant." (PMID 41006206, 2025). "A similar phenomenon occurs in the cells of patients with galactosialidosis with a genetic deficiency of CTSA leading to disruption of the LMC." (PMID 40540388, 2025). "Galactosialidosis (GS) is a lysosomal accumulation disorder caused by pathogenic variants in the CTSA gene located at 20q13.12." (PMID 41006206, 2025). "Functionally, lysosomal CTSA is part of a multienzyme complex, and it is required to stabilize β-galactosidase and activate neuraminidase 1 and mutations in the CTSA gene have been linked with galactosialidosis." (PMID 38775843, 2024). "Seven patients with sialidosis type I (mutations in NEU1) and one with galactosialidosis (mutations in CTSA) were included." (PMID 32753397, 2021). "The enzymatic activity of NEU1 is activated/stabilized by cathepsin A. Cathepsin A dysfunctions due to mutations in CTSA (cathepsin A gene) causes galactosialidosis (OMIM # 256540), which is characterized by similar symptoms to those of sialidosis." (PMID 34188220, 2021). "Galactosialidosis (GS) is a rare multisystem glycoprotein storage disease caused by mutation in the CTSA gene." (PMID 32162101, 2020). "Galactosialidosis (GS) is an autosomal recessive disease caused by mutations inthe Cathepsin A gene (CTSA) that encodes the protectiveprotein/cathepsin A (PPCA)." (PMID 31132295, 2019). "Mutations in the CTSA gene cause galactosialidosis in humans and secondary deficiencies of beta-galactosidase and neuraminidase." (PMID 30018533, 2018). "CARASAL patients share a dominant c.973C>T, p.(Arg325Cys) mutation in the CTSA gene encoding cathepsin A. Recessive CTSA mutations cause galactosialidosis, a rare systemic lysosomal storage disorder." (PMID 28638987, 2017). "Genetic deficiency of the cathepsin A protein leads to reduced levels of β-galactosidase and results in the lysosomal storage disease galactosialidosis." (PMID 27246731, 2016). "Molecular defect of the CTSA cause autosomal recessively inherited rare lysosomal storage disease; galactosialidosis." (PMID 27826550, 2016). "Family 13DG1635 had a homozygous truncating mutation in CTSA, which predicts galactosialidosis, a known cause of NIHF." (PMID 26036949, 2015). "Finally, in humans, CTSA mutations leading to loss of or reduced CtsA activity are linked to the onset of Galactosialidosis, also known as neuraminidase deficiency with β-galactosidase deficiency, which is included among glycoproteinoses." (PMID 39851495, 2025). "Interestingly, mutations in cathepsin A generate significant protein deposits in the cell associated with galactosialidosis." (PMID 37628828, 2023). "Galactosialidosis is a glycoprotein storage disease caused by an inherited deficiency of the lysosomal protective protein/cathepsin A (PPCA) which is associated in a complex with both, α-neuraminidase (sialidase, NEU1, EC 3.2.1.18) and acid β-galatosidase (β-Gal, EC 3.2.1.23)." (PMID 32272755, 2020). "Thus far, 19 disease-causing mutations have been identified for galactosialidosis in the CTSA gene, the majority of which were missense mutations resulting in single amino acid substitutions." (PMID 31484286, 2019). "Recessive CTSA mutations cause galactosialidosis due to deficiency of these enzymes." (PMID 28638987, 2017). "Deficiency of cathepsin A leads to the lysosomal storage disease, galactosialidosis, in human." (PMID 19208265, 2009).
galactosialidosis (continued). "Thus, mutation analysis of the patient’s CTSA gene and biochemical assessment of the cathepsin A, β-galactosidase, and neuraminidase-1 activities in cultured fibroblasts should be performed to support the diagnosis of early infantile galactosialidosis." (PMID 31484286, 2019). "Galactosialidosis (GS, OMIM #256540) is a rare autosomal recessive glycoprotein storage disease caused by mutations in the cathepsin A (CTSA) gene, which is composed of 15 exons." (PMID 39981487, 2025). "Galactosialidosis (GSL), or Goldberg syndrome [OMIM#256540], is an AR LSD caused by homozygous or compound heterozygous mutations affecting the gene encoding cathepsin A (CTSA, also known as PPCA) on chromosome 20q13." (PMID 37239976, 2023). "Galactosialidosis (GS, OMIM #256540) is a systemic autosomal recessive disorder that is due to a mutation in the cathepsin A (CTSA) gene." (PMID 36341164, 2022). "More specifically, the lysosomal storage disorder Galactosialidosis (GS), caused by the loss of function of PPCA/CTSA, results in the secondary combined deficiency of GLB1 and NEU138." (PMID 31776384, 2019). "Mutations in the CTSA gene, that encodes the protective protein/cathepsin A or PPCA, lead to the secondary deficiency of β-galactosidase (GLB1) and neuraminidase 1 (NEU1), causing the lysosomal storage disorder galactosialidosis (GS)." (PMID 23915561, 2013). "It was worthwhile to investigate whether heterozygous CTSA mutations were associated with an increased risk of SVD, particularly in patients with galactosialidosis." (PMID 31484286, 2019). "In addition, the genetic deficiency of CTSA results in the secondary deficiencies of NEU1 and GLB1, and causes the lysosomal storage disorder (LSD) galactosialidosis (GS OMIM #256540)." (PMID 30088207, 2018). "In mice, expression of catalytically inactive cathepsin A in lieu of the wild-type variant does not cause galactosialidosis, highlighting that cathepsin A enzymatic activity is not linked to its role in protecting β-galactosidase and neuraminidase." (PMID 27246731, 2016). "Although, the markedly increased endothelin-1-specific immunoreactivity has been demonstrated in CTSA deficient galactosialidosis patient's brain, we did not observe any difference neither in brain nor in liver from CTSAS190A mice using ELISA." (PMID 27826550, 2016). "Galactosialidosis (GSL, OMIM ID: 256540) is an autosomal recessive LSD caused by mutations in the gene encoding CTSA." (PMID 32326609, 2020). "This opens to the possibility, not investigated so far, that heterozygous carriers of CTSA mutations causing galactosialidosis may also be at risk for small vessel disease." (PMID 28638987, 2017). "Defects in CTSA, CTSD, CTSF, and CTSK result in galactosialidosis, neuronal ceroid lipofuscinoses (NCLs) type 10 and type 13, and pycnodysostosis, respectively." (PMID 32326609, 2020).
Leukoencephalopathy (20 papers, 2017 to 2026). This term describes abnormality of the white matter of the cerebrum resulting from damage to the myelin sheaths of nerve cells. "CTSA-associated arteriopathy with stroke and leukoencephalopathy, which is a rare genetic adult small vessel disease of the human brain, is caused by mutations in the CTSA gene and is a late feature of slow cognitive dysfunction." (PMID 39122455, 2024). "It is of interest that mutations in a related cathepsin gene, CTSA, has been implicated in an independent inherited SVD, Cathepsin A-related arteriopathy with strokes and leukoencephalopathy (CARASAL)." (PMID 36753487, 2023). "More recently, the autosomal dominant cathepsin A-related arteriopathy with strokes and leukoencephalopathy (CARASAL) caused by pathogenic variants in CTSA (Cathepsin A) was described." (PMID 35976293, 2022). "Cathepsin A-related arteriopathy with strokes and leukoencephalopathy (CARASAL) is an adult-onset leuko-vasculopathy caused by a dominant mutation in CTSA, encoding cathepsin A (CathA)." (PMID 34082828, 2021). "This very recently described entity due to heterozygous mutations in the CTSA gene is named cathepsin A-related arteriopathy with strokes and leukoencephalopathy (CARASAL)." (PMID 30467211, 2019). "Cathepsin A-related arteriopathy with strokes and leukoencephalopathy (CARASAL) is an extremely rare, and very recently described, condition associated with heterozygous mutations in the CTSA gene." (PMID 35163523, 2022). "Cathepsin A-related arteriopathy with strokes and leukoencephalopathy (CARASAL) is a recently identified adult-onset leukodystrophy caused by a dominant mutation in the CTSA gene encoding for cathepsin A (CathA)." (PMID 35227276, 2022). "We identified a single patient with the recently described syndrome of cathepsin A-related arteriopathy with strokes and leukoencephalopathy (CARASAL)." (PMID 28334938, 2017). "Lastly, high levels of ET-1 in the SVZ of patients with Cathepsin A-related arteriopathy with strokes and leukoencephalopathy correlate with an increased number of SVZ OPCs, suggesting ET-1’s role as a regulator of glial progenitor proliferation may be conserved in humans." (PMID 32358570, 2020). "Finally, we show that elevated ET-1 protein in the adult human SVZ of Cathepsin A-related arteriopathy with strokes and leukoencephalopathy (CARASAL) patients correlates with increased numbers of astrocytes and OPCs, indicating that ET-1 signaling plays a similar role in the human SVZ." (PMID 32358570, 2020). "A patchy leukoencephalopathy with lacunes, microhaemorrhages and anterior temporal lobe involvement is suggestive of a vascular disorder such as CADASIL or cathepsin A-related arteriopathy with strokes and leukoencephalopathy (CARASAL)." (PMID 30467211, 2019). "Nevertheless, for SVD patients with a positive family history, an unusual extensive leukoencephalopathy, and an absence of NOTCH3, HTRA1, and COL4A1/A2 mutations, a molecular analysis of the CTSA gene should be considered." (PMID 31484286, 2019).
Stroke (18 papers, 2017 to 2026). Sudden impairment of blood flow to a part of the brain due to occlusion or rupture of an artery to the brain. "Cognitive features were the most common clinical cerebral phenotype for 4 of 7 genes (HTRA1HomZ, COL4A2, HTRA1HetZ, and CTSA); stroke was the most common among individuals with COL4A1 and ADA2, and headache was most common among individuals with TREX1." (PMID 35699195, 2022). "The frequency of clinical stroke ranged from 22% to 52% for 6 of 7 genes (COL4A2, 22% [9/41]; HTRA1HomZ, 30% [13/44]; ADA2, 33% [115/346]; COL4A1, 41% [161/390]; CTSA, 50% [7/14]; HTRA1HetZ, 52% [43/82]), while only 9% (11/123) of TREX1 individuals were reported to have suffered a clinical stroke." (PMID 35699195, 2022).
lysosomal storage disorder (7 papers, 2009 to 2025). "Homozygous CTSA mutation is thought to cause CARASAL by interfering with the function of cathepsin A, which protects against a systemic lysosomal storage disorder by stabilising the lysosomal enzymes β‐galactosidase and neuraminidase." (PMID 36564356, 2023).
liver cancer (5 papers, 2021 to 2025). An epithelial or non-epithelial malignant neoplasm that arises from the liver. "CTSA, CRELD2, MAPK10, and other specific genes are associated with the Ras and MAPK signaling pathways, which have been implicated in tumorigenesis and metastasis of hepatic cancer." (PMID 40901642, 2025). "Besides, the human body map shows that the mRNA expression level of CTSA is significantly up-regulated in liver cancer tissues compared with normal liver." (PMID 34272452, 2021). "Finally, we detected the expression of CTSA in normal liver cell lines (LO2) and liver cancer cell lines (BEL7402, HEPG2, HCCLM3), and the results showed that the expression level of CTSA in liver cancer cell lines was significantly higher than that in normal liver cell lines." (PMID 37287981, 2023). "First, we detected the expression of CTSA in liver cancer cell lines (BEL7402, HEPG2, HCCLM3) and normal liver cell lines (LO2), and the results showed that the expression level of CTSA in liver cancer cell lines was significantly higher than that in LO2 cells." (PMID 37437243, 2023).
CARASIL (4 papers, 2019 to 2024). CARASIL is a hereditary cerebral small vessel disease characterized by early-onset gait disturbances, premature scalp alopecia, ischemic stroke, acute mid to lower back pain and progressive cognitive disturbances leading to severe dementia. "A number of different genes come under the umbrella term of vascular leukoencephalopathies, including NOTCH3 (CADASIL), HTRA1 (cerebral autosomal recessive arteriopathy with subcortical infarcts and leukoencephalopathy (CARASIL)), CTSA (CARASAL), COL4A1 and TREX1." (PMID 30467211, 2019).
sialidosis (4 papers, 2020 to 2024). "Another type of sialidosis is due to the absence of cathepsin A (PPCA) that prevents enzyme complex formation and thus depletes lysosomal activity of both sialidase NEU1 and β-galactosidase, causing accumulation of GM1 and other GSLs." (PMID 32961778, 2020).
hepatocellular carcinoma (3 papers, 2021 to 2024). A malignant tumor that arises from hepatocytes. "In hepatocellular carcinoma (HCC), upregulation of cathepsin A and H correlates with poor prognosis." (PMID 39736788, 2024). "However, rarely the previous study has addressed the role of CTSA in hepatocellular carcinoma (HCC) and its prognostic value." (PMID 34272452, 2021).
melanoma (3 papers, 2018 to 2022). A malignant, usually aggressive tumor composed of atypical, neoplastic melanocytes. "Cellular levels of mature and precursor forms of lysosomal proteases cathepsin A and cathepsin B were unchanged in melanoma cells by ectopic LAMP-2C." (PMID 30211163, 2018). "Similar results have been found for cathepsin A in malignant melanoma and cathepsin B in non-small cell lung carcinoma and in OSCC." (PMID 29618339, 2018). "At 1 μM, lactacystin suppressed the cathepsin A activity in B78 melanoma cell lysate by about 50%." (PMID 35910377, 2022). "Quantitative analysis of transcripts for cathepsin genes CTSA, CTSB, and CTSD corroborated that ectopic expression of LAMP-2C in melanoma cells did not increase the expression of these lysosomal enzyme mRNAs." (PMID 30211163, 2018).
Obesity (3 papers, 2012 to 2024). Accumulation of substantial excess body fat. "In GWAS analysis, the genes CYP3A5, SLC24A3 and CTSA are observed in obesity related diseases like Hypertensive disease, Asthma, Coronary Artery Disease, Essential Hypertension, Hypertensive disease and Heart failure." (PMID 32027667, 2020). "In our analysis CTSA is co-expressed with obesity related genes suggesting a critical role in the pathway of obesity since the members of Cathespin family plays import role in obesity." (PMID 32027667, 2020). "A recent study identified six proteins (LEPR, IGFBP1, WFIKKN2, AGER, DPT, and CTSA), including WFIKKN2, which may have a causal role in the development of obesity." (PMID 39273278, 2024). "Notably, CYP3A5 and CTSA formed two separate networks with connectivity 6 and 3 respectively to obesity related gene." (PMID 32027667, 2020). "The function of cathepsin A in obesity is relatively unknown, however increases in expression of cathepsin B, D, K, S, and Z have previously been observed in obesity." (PMID 22947075, 2012).
breast carcinoma (2 papers, 2020 to 2022). "We also took our RNA-Seq data into consideration, including proteases like OTUD5, which was significantly upregulated in all three breast cancer cell lines, or Cathepsin A that was significantly upregulated in MCF7 and MDA-MB-231 cells." (PMID 35673573, 2022). "For breast cancer, we select five essential genes, such as CTSA, HSPA2, RNASE1, CLIC6, IFITM1." (PMID 33133130, 2020).
colorectal cancer (2 papers, 2020 to 2025). A primary or metastatic malignant neoplasm that affects the colon or rectum. "Although high CTSA expression was associated with poorer outcome in breast ductal carcinoma in situ, it was also found to suppress invasion and metastasis of colorectal cancer, suggesting tissue-specific differential roles." (PMID 33237942, 2020). "The opposing effects of miR-106b-5p on migration and invasion in colorectal cancer, depending on whether it targets FAT4 or CTSA, underscore the complexity of miRNA function and the possibility that different regulatory networks become dominant in different stages or subtypes of colorectal cancer." (PMID 41155295, 2025).
COVID-19 (2 papers, 2021 to 2024). A disease caused by infection with severe acute respiratory syndrome coronavirus 2. "Several drugs targeting CTSA have been approved for the treatment of chronic hepatitis B virus infection, hepatitis C virus infection and RNA virus infections including COVID-19." (PMID 38614964, 2024).